BRCA2 (BRCA2 DNA repair associated)
Diseases named in the same sentence as BRCA2 in open-access papers (continued):
Sharing a sentence is not in itself a finding about the gene and the disease.
breast cancer (continued). "In contrast, only 56.9% of BRCA2 carriers and 11.3% of patients over 60 years old received chemotherapy for an index breast cancer diagnosis." (PMID 40275390, 2025). "A meta-analysis evaluated the association between the incidence of breast cancer and HRT in 1100 women carrying BRCA1 and BRCA2 P/LP variants and intact breasts who underwent bilateral salpingo-oophorectomy (RRSO) before the onset of natural menopause." (PMID 39858629, 2025). "For females ≥18 years with a GPV in BRCA1, BRCA2 or PALB2, a referral to the very high-risk breast cancer screening (VHRS) programme or equivalent should be made at the time of diagnosis." (PMID 41159931, 2025). "The lifetime risk of developing breast cancer is significantly higher among women with inherited risk factors for breast cancer, especially those with the BRCA1 and BRCA2 pathogenic variants." (PMID 41083355, 2025). "An estimated 40% (95% CI, 35%–45%) of BRCA1 carriers and 26% (95% CI, 20%–33%) of BRCA2 carriers develop contralateral breast cancer within 20 years following an initial breast cancer diagnosis." (PMID 41083355, 2025). "Among the non-modifiable factors, genetic mutations in the Breast Cancer Gene 1 and Breast Cancer Gene 2 (BRCA1 and BRCA2) are the most common alterations in breast cancer." (PMID 40417678, 2025). "Our results align with previous studies examining the relationship between OC use and breast cancer risk in BRCA1 and BRCA2 mutation carriers." (PMID 41327462, 2025). "For the BRCA1, BRCA2, PALB2, CHEK2, and ATM genes, most protein-truncating variants have been associated with a high risk of breast cancer." (PMID 39858629, 2025). "Breast cancer associated with BRCA1 and BRCA2 mutations presents unique therapeutic challenges, traditionally favoring mastectomy due to concerns over recurrence and new primaries." (PMID 41302125, 2025). "For PALB2 carriers, breast cancers are felt to be biologically similar to BRCA2 cases, however there remains a paucity of data on breast cancer treatment and outcomes." (PMID 40275390, 2025). "We focused on Polish founder mutations in BRCA1, BRCA2, PALB2, CHEK2, NBN and RECQL (18 alleles), which account for one-half of Polish breast cancer families." (PMID 40770660, 2025). "In contrast, for the breast cancer data, we use the known mutation information (BRCA1 and BRCA2) but employ K-means clustering to identify gene groups through from the genes' embeddings." (PMID 41542084, 2025). "BRCA2 and HER2, both being broadly known to be associated with breast cancer, serve as a point of confirmation of the efficacy of AutoEpiCollect 2.0." (PMID 41471728, 2025). "In breast cancer, olaparib and talazoparib are approved for BRCA1/BRCA2-mutated, HER2-negative metastatic TNBC." (PMID 40864792, 2025). "There is also an association between BRCA2 loss and increased FANCD2 mRNA levels in breast cancer cell lines and tumors." (PMID 40669753, 2025). "RRM has decreased the relative risk of breast cancer in healthy BRCA1 and BRCA2 P/LP variant carriers by 90–95%." (PMID 39858629, 2025). "Next, the in vivo efficacy of RTx-303 was evaluatedat 60 mg/kg(po, bid) as a single agent and in combination with olaparib againsta BRCA2 mutant breast cancer PDX model (BR-05–0566)in BALB/c mice." (PMID 41124685, 2025). "Twenty-four individuals (16.8% [95% CI, 11.1%-23.9%]) with germline testing had PGVs in breast cancer susceptibility genes, including BRCA1 (n = 17 [70.8%]), BRCA2 (n = 5 [20.8%]), PALB2 (n = 1 [4.2%]), and CHEK2 (n = 1 [4.2%])." (PMID 39964682, 2025). "Most breast cancer susceptibility genes are involved in the damage repair signaling pathway, i.e., including BRCA1, BRCA2, PALB2, CHEK2, ATM, BARD1, RAD51C, and RAD51D." (PMID 40649769, 2025).
breast cancer (continued). "This is in parallel with variants in genes implicated in hereditary breast cancer including the ‘high risk’ genes BRCA1, BRCA2, and PALB2 and ‘moderate risk’ genes CHEK2 and ATM." (PMID 41327266, 2025). "As a tumor suppressor gene, BRCA2 is involved in regulating the follicular pool through impairment of the DNA repair pathway and can affect ovarian reserves in breast cancer patients." (PMID 41153822, 2025). "The GEN1 gene is implicated in DNA damage repair, as are several high- or moderate-risk breast cancer susceptibility genes, i.e., BRCA1, BRCA2, PALB2, CHEK2, ATM, and BRIP1." (PMID 40649769, 2025). "For instance, B3GNT7 and CTSV predicted detrimental prognosis in BRCA2-mut breast cancers, and CD6, CXCL9, and CXCL13 predicted favorable outcomes in BRCA1-mut ovarian cancers." (PMID 40647506, 2025). "BRCA2 (Breast Cancer 2) is a very important gene when it comes to the integrity of DNA, as it loads Rad51 into single-stranded DNA regions." (PMID 40650308, 2025). "According to a prospective study, the risk of developing breast cancer by age 80 years is 72% for those with a BRCA1 mutation and 69% for those with a BRCA2 mutation." (PMID 40942929, 2025). "For patients with pathogenic variants of the genes BRCA1/BRCA2, the OlympiA trial achieved positive results in a high-risk population of hormone receptor-positive, HER2-negative breast cancers and variants of the genes BRCA1/BRCA2." (PMID 40002156, 2025). "Breast cancer susceptibility genes 1 and 2 (BRCA1 and BRCA2) are two key tumor suppressor genes involved in this process." (PMID 40429877, 2025). "Since these mechanisms are also essential for effective tumor cytotoxicity, we explore tumor-specific effects, particularly in hereditary breast cancer linked to BRCA1 and BRCA2 mutations." (PMID 39621070, 2025). "In breast carcinoma, epitopes with the highest potential were derived from proteins expressed by BRCA2 and AHNAK2." (PMID 41471728, 2025). "Conditional deletion of exons 3 and 4 of Brca2 leads to breast carcinoma development when Cre expression is driven by the Wap promoter." (PMID 40854122, 2025). "While 75% of BRCA2-associated breast cancers are reported to be HR+, approximately 70% of BRCA1-associated breast cancers are TNBC20–23." (PMID 39060255, 2024). "In fact, the most frequent risk factors responsible for BC onset are hereditary and genetic, such as breast cancer or ovarian cancer history and inherited mutations, in particular BRCA1 and BRCA2." (PMID 39141659, 2024). "In Asian populations, studies were done on unselected breast cancer germline mutation spectra, the mutation rates ranged from 1.5% to 2.7% for BRCA1 and 2.4% to 3.8% for BRCA2." (PMID 39272924, 2024). "We found evidence of a statistically significant association with breast cancer risk for three genes, with ORs of 16.3 [95% CI: 4.0–66.7] (p = 0.0001) for BRCA1, 12.0 [95% CI: 2.9–45.9] for BRCA2 (p = 0.0001), and 7.3 [95% CI: 0.9–56.7] (p = 0.037) for ATM." (PMID 39684352, 2024). "Risk-reducing bilateral salpingo-oophorectomy (RRSO) is recommended for breast cancer gene 1 (BRCA1) and 2 (BRCA2) mutation carriers." (PMID 38256099, 2024). "Although susceptibility to breast cancer in BRCA1 and BRCA2 mutation carriers has been known for several decades, mechanisms responsible for this susceptibility are just beginning to be identified, largely due to recent advances in single-cell technologies." (PMID 38059556, 2024). "A recent study suggests that AURKA-HMMR, a genetic variant of AURKA, is linked to increased breast cancer risk in BRCA1 and BRCA2 mutation carriers." (PMID 38886738, 2024). "This economic evaluation estimates the cost-effectiveness of prevention strategies for ovarian and breast cancer among individuals with pathogenic variants in cancer susceptibility genes BRCA1, BRCA2, PALB2, RAD51C, RAD51D, and BRIP1." (PMID 38334999, 2024). "We next analyzed patient survival with respect to MLH1 status in BRCA2-low breast cancer patient samples." (PMID 38271119, 2024).
breast cancer (continued). "Pathogenic variants (PVs) in BRCA1, BRCA2, PALB2, RAD51C, RAD51D, and BRIP1 cancer susceptibility genes (CSGs) confer an increased ovarian cancer (OC) risk, with BRCA1, BRCA2, PALB2, RAD51C, and RAD51D PVs also conferring an elevated breast cancer (BC) risk." (PMID 38334999, 2024). "Mutations in the breast cancer 1 gene (BRCA1) and breast cancer 2 gene (BRCA2) are among the most well‐known causes of autosomal dominant breast cancer." (PMID 38140764, 2024). "In this subgroup, the cumulative risk of developing breast cancer up to the age of 80 years is about 72% in BRCA1 and 69% in BRCA2 pathogenic variant carriers." (PMID 38892081, 2024). "Approximately 5% to 10% of breast cancer (BC) cases can be associated with a genetic predisposition, among which BRCA1 and BRCA2 are the most commonly involved genes." (PMID 38564263, 2024). "In certain populations, more prevalence of germline mutations related to breast cancer such as BRCA1, BRCA2 is observed." (PMID 39684874, 2024). "The second most important factor associated with the incidence of breast cancer is the gene gent mutation of BRCA1 and BRCA2." (PMID 38473036, 2024). "The Breast Cancer Linkage Consortium study showed that carriers of BRCA2 PVs were 2.5 times more likely to develop melanoma compared to the general population." (PMID 38974244, 2024). "The cumulative risk of developing breast cancer by age 70 is approximately 55%–70% for individuals carrying BRCA1 mutations and 45%–70% for those carrying BRCA2 mutations." (PMID 39421188, 2024). "A study on Springer spaniels revealed a significant association between the development of mammary tumours and BRCA1 and BRCA2 polymorphisms, with 97% of diagnosed cases possessing these alleles." (PMID 38573417, 2024). "We discovered the involvement of MBD protein in the control of BRCA1, BRCA2, and p16, as well as their impacts on breast cancer cells, in this work." (PMID 38711004, 2024). "Compared with BRCA2 variant carriers (80 [46.5%]), women with BRCA1 variants (92 [53.5%]) were younger at breast cancer diagnosis and tended to have more advanced tumors, which were more likely to be hormone receptor negative and higher grade." (PMID 38916888, 2024). "The interplay between DNA damage and autophagy is heavily influenced by DNA-damage repair (DDR) genes, such as breast cancer susceptibility genes 1 and 2 (BRCA1/BRCA2), and Fanconi anemia (FA) genes." (PMID 39199310, 2024). "Nevertheless, RRSO is associated with a significant reduction in PBC risk in BRCA2 carriers alone and improved breast cancer survival in BRCA1 and BRCA2 carriers previously diagnosed with breast cancer." (PMID 38256099, 2024). "Previous studies have also suggested that the CASP8 D302H polymorphism decreases breast cancer risk associated with BRCA1 and BRCA2 mutations, delaying cancer onset." (PMID 39351539, 2024). "Her group compared BRCA1/2 mutation carriers who chose RRBM versus those who preserved their breasts and concluded that, in women with a BRCA1 or BRCA2 pathogenic variant, RRBM reduced the risk of breast cancer (HR 0.20)." (PMID 38717180, 2024). "Genetic testing for breast cancer predisposing genes has expanded beyond BRCA1 and BRCA2 and now includes panels of 20 or more genes." (PMID 39543654, 2024). "Many studies, including two meta-analyses, showed that prophylactic bilateral mastectomy reduces the risk for breast cancer in unaffected women with BRCA1 [relative risk (RR)= 0.134, 95% CI, 0.019–0.937] and BRCA2 (RR= 0.183, 95% CI, 0.072–0.468)." (PMID 39507757, 2024). "The lifetime risk of developing breast cancer is increased to 40–80% in individuals who carry mutations in the BRCA1 and BRCA2 genes." (PMID 39096427, 2024).
breast cancer (continued). "In contrast, the probability of developing breast cancer in men with BRCA1 and BRCA2 mutations is 1.2% and 8.9%, respectively." (PMID 38543119, 2024). "A genetic risk factor can be identified in 5–15% of breast cancers, most commonly mutations in BRCA1 or BRCA2, tumor suppressor genes associated with DNA damage repair." (PMID 38365640, 2024). "We next focus on the gene modules of BRCA1 and BRCA2, which are the most commonly encountered genes in breast cancer." (PMID 39013885, 2024). "The best known are BRCA1 and BRCA2 which convey average lifetime breast cancer risks of 50% to 70% and significant risks for ovarian cancer and other malignancies." (PMID 39107016, 2024). "In a meta-analysis of 10 studies, there was a 57% risk for developing breast cancer before the age of 70 in women with BRCA1 pathogenic variants, and 49% in women with BRCA2 pathogenic variants." (PMID 38365640, 2024). "High-grade serous ovarian carcinoma (HGSOC) is the most prevalent histological subtype of epithelial ovarian cancer and is associated with mutations in the breast cancer susceptibility genes 1 and 2 (BRCA1 and BRCA2) in approximately 25% of cases." (PMID 39314634, 2024). "Germline BRCA1/2 mutation carriers have a high incidence of breast cancer in their lifetime; the lifetime probability is approximately 57–65% for those with BRCA1 mutations and 45–49% for those with BRCA2 mutations." (PMID 38869771, 2024). "Kuchenbaecker et al20 estimated contralateral breast cancer risk at 20 years to be 40% for BRCA1 variant carriers, but only 26% for BRCA2 variant carriers." (PMID 38916888, 2024). "For BRCA2, the corresponding cohort effect for breast cancer were of 1.4 (1.1–2.2), 2.2 (1.4–3.4) and 4.4 (2.3–8.5)." (PMID 38333895, 2024). "Approximately 84% of hereditary breast cancers and more than 90% of hereditary ovarian cancers are caused by mutations in BRCA1 and BRCA2 genes." (PMID 38256099, 2024). "For BRCA1, peak breast cancer incidence occurs between 41 and 50 years, whereas for BRCA2 and PALB2, peak incidence occurs between 51 and 60 years of age." (PMID 38248108, 2024). "In Thailand, the universal reimbursement of germline BRCA1 and BRCA2 genetic testing for breast cancer patients has been approved since 2022." (PMID 38355628, 2024). "Pathogenic variants (PVs) in the BRCA1 and/or BRCA2 (BRCA1/2) genes are associated with high risks of developing first and contralateral breast cancer (BC) and ovarian cancer (OC)." (PMID 39446752, 2024). "We used data from two large studies to update the breast cancer risks in the BOADICEA model for BRCA2 carriers 60 years and older." (PMID 39072245, 2024). "Concerning blood folate levels, high plasma levels of B9 have been associated with an increased risk of breast cancer in women with BRCA1 and BRCA2 mutations." (PMID 39125744, 2024). "In BRCA2, multiple breast cancer cluster regions (BCCRs) spanning c.1 to c.596, c.772 to c.1806 and c.7394 to c.8904 were identified." (PMID 37956396, 2024). "We found that breast cancer susceptibility variants in BRCA1, BRCA2, ATM, and CHEK2 were associated with development of CBC in a subtype-specific manner." (PMID 39786405, 2024).
breast cancer (continued). "The proportion of breast cancers in the general population attributed to BRCA1 and BRCA2 germline pathogenic variants is approximately 5–10%, but this proportion is much higher (up to 55%) in selected families referred to familial cancer clinics." (PMID 39402389, 2024). "The PVs in high-risk (BRCA1, BRCA2, PALB2) or moderate-risk (ATM, CHEK2) genes mainly associated with breast cancer in women follow an autosomal dominant inheritance pattern." (PMID 38722431, 2024). "Among Ashkenazi Jewish breast cancer patients, a higher BRCA1 and BRCA2 mutation rate was found to be associated with a family history of pancreatic cancer." (PMID 39595558, 2024). "Currently, no studies exist regarding the influence of hormonal contraceptives on breast cancer risk in carriers of pV in breast and/or ovarian cancer genes other than BRCA1 and BRCA2." (PMID 39259360, 2024). "Heterozygous mutations in any of three major genes, BRCA1, BRCA2 and PALB2, are associated with high-risk hereditary breast cancer susceptibility frequently seen as familial disease clustering." (PMID 38597967, 2024). "To date, no clear association exists between BRCA1/2 mutations and GIST, with only rare reports available, including a patient harboring simultaneous BRCA2 and KIT germline mutations manifesting as breast cancer and multiple GISTs, respectively." (PMID 39199677, 2024). "Her father is a prostate cancer survivor, and her mother tested BRCA2+ and died from breast cancer at the age of 52." (PMID 38730719, 2024). "Mutations in the BRCA1 and BRCA2 genes increase the risk of breast cancer, with cumulative risks of 72% for BRCA1 and 69% for BRCA2 mutation carriers." (PMID 38256428, 2024). "Ten percent of patients with breast cancer, and probably somewhat more in patients with ovarian cancer, have inherited germline DNA mutations in the breast and ovarian cancer genes BRCA1 and BRCA2." (PMID 38540206, 2024). "There is evidence that BRCA1/2-mutated tumors exhibit significantly increased CD8+ TILs, although in breast cancer, differential modulation between BRCA1 and BRCA2 mutations in the tumor immune microenvironment has been found." (PMID 39669575, 2024). "Olaparib, the first poly(ADP-ribose) polymerase (PARP) inhibitor to be developed, is effective in treating women with breast cancer who have germline pathogenic variants in BRCA1 and/or BRCA2 (gBRCAm), both in the metastatic and the adjuvant setting." (PMID 38588696, 2024). "Women who underwent RRSO had a lower risk of first diagnosis of breast cancer in BRCA1 mutation carriers; 20% vs 14% (HR= 0.63, 95% CI, 0.41-0.96) and BRCA2 mutation carriers; 23% vs 7% (HR= 0.36, 95% CI, 0.16-0.82)." (PMID 39507757, 2024). "A significant retrospective study from the Breast Cancer Linkage Consortium revealed an elevated chance of uterine cancer for BRCA1 mutation carriers, but weren’t for BRCA2 mutation carriers (RR = 2.65; 95% CI: [1.69,4.16]; P < 0.001)." (PMID 38297203, 2024). "USP11 has been identified to bind to the C-terminal of BRCA2 (2281-3418) and stabilize BRCA2 protein through deubiquitination, thus participating in DNA damage repair of breast cancer." (PMID 39617751, 2024). "In BRCA2-mutant breast cancer, ATR inhibitors in combination with olaparib can also boost antigen presentation and inflammation in the TME by abrogating PDL1 upregulation and Treg cell recruitment." (PMID 38473997, 2024). "Men carrying BRCA2 variants, and to a lesser extent BRCA1 variants, also exhibit heightened predispositions to breast cancer and prostate cancer." (PMID 38809921, 2024).